MTOR (mechanistic target of rapamycin kinase)
Diseases named in the same sentence as MTOR in open-access papers (continued):
Sharing a sentence is not in itself a finding about the gene and the disease.
non-small cell lung carcinoma (362 papers, 2006 to 2026). A group of at least three distinct histological types of lung cancer, including non-small cell squamous cell carcinoma, adenocarcinoma, and large cell carcinoma. "Non-small cell lung cancers (NSCLC) are associated with constitutive activation of the PI3K-Akt-mTOR pathway." (PMID 38164273, 2024). "Overexpression of MOR in non-small-cell lung cancer cells was associated with enhanced tumor progression and higher Akt and mTOR activation." (PMID 38920719, 2024). "Downstream of the PI3K/Akt, the mechanistic Target of Rapamycin (mTOR) is highly associated with PD-L1 expression in non-small-cell lung cancer models." (PMID 38539569, 2024). "We correlated the expression of hamartin, p-TSC2 and p-mTOR with expression data concerning epidermal growth factor receptor mutations in non-small cell lung cancer and their influence on downstream Akt, MAPK and Stat3 signaling." (PMID 24593867, 2014). "Thus, 6-shogaol was shown to induce autophagy associated with inhibiting the AKT/mTOR pathway in the human non-small cell lung cancer A549 cells and in cervical carcinoma HeLa and SiHa cells." (PMID 39199328, 2024). "Additionally, AKT/mTOR pathway has been closely associated with EMT; for example, in liver cancer and non-small cell lung cancer, mTOR signaling pathway activation induces EMT and subsequently accelerates tumor progression." (PMID 39593172, 2024). "This is consistent with recent studies reporting autophagy promotion upon cycloastragenol treatment through the AMPK/ULK1/mTOR pathway in human non-small-cell lung cancer lines or via Notch1 signaling in human keratinocytes." (PMID 41596421, 2026). "■Salicylic acid derivative;■Investigational for non-small-cell lung carcinoma (phase 2);■Serine/threonine-protein kinase mTOR modulator; GTPase NRas antagonist." (PMID 40298549, 2025). "For example, the expression of CD39 and CD73 in myeloid-derived suppressor cells (MDSCs) is induced through TGF-β-mTOR-HIF-1 signaling in patients with non-small cell lung cancer." (PMID 40141056, 2025). "GA-DM promotes autophagic flux and cytotoxic effects against non-small-cell lung cancer by inhibiting the Akt/mTOR pathway." (PMID 40573305, 2025). "Clinical implications of the interaction between the PD-1/PD-L1 and PI3K/AKT/mTOR pathway have been reviewed, focusing on patients suffering from non-small-cell lung cancer (NSCLC)." (PMID 40149335, 2025). "Another study in non-small cell lung cancer showed that miR-193a-5p downregulates the mTOR/PIK3R3 signaling pathway, inhibiting the migration, invasion, and EMT of NSCLC cells." (PMID 40161373, 2025). "VD reportedly affects the Warburg effect and stemness maintenance in non-small cell lung cancer cells by regulating the PI3K/AKT/mTOR signaling pathway." (PMID 41392241, 2025). "CCL2 promotes the metastasis and EMT of non-small cell lung cancer through the PI3K/AKT/mTOR axis and autophagy signaling pathways." (PMID 40229278, 2025). "Previous studies have shown that FGFC1 inhibits the PI3K/Akt/mTOR and NF-κB pathways in non-small-cell lung cancer." (PMID 40894196, 2025). "Several studies also reported that 6-shogaol inhibited mTOR and induced cell death in non-small cell lung cancer and cervical carcinoma cells." (PMID 39199328, 2024). "The study of inhibiting mTOR in non-small cell lung carcinoma shows a reduced PD-L1 expression level." (PMID 38370876, 2024). "The study reveals the reduced of PD-L1 level in non-small cell lung carcinoma that inhibit mTOR by rapamycin." (PMID 38370876, 2024). "Examples include afatinib-celastrol against non-small cell lung cancer cells, paclitaxel-honokiol against non-small cell lung cancer cells, and the mTOR inhibitor jolkinolide B in bladder cancer cells." (PMID 39497143, 2024). "The antitumor properties and molecular mechanisms of fucoidan have been further validated in non-small-cell lung cancer models, where it inhibited angiogenesis via the mTOR signaling pathway." (PMID 39770896, 2024).
non-small cell lung carcinoma (continued). "Inhibiting ULK1 has shown promise in sensitizing CSCs to chemotherapy, as evidenced by the ULK1 inhibitor SBI-0206965, which, in combination with mTOR inhibitor, increases cisplatin sensitivity in non-small cell lung cancer." (PMID 39456967, 2024). "PTEN deficiency in non-small cell lung cancer results in increased PI3K/ AKT signaling pathway and downstream mTOR, which affects a variety of cellular activities." (PMID 38965615, 2024). "Docosahexaenoic acid, a 22-carbon omega-3 fatty acid, induces cell death in human non-small cell lung cancer cells by inhibiting mTOR through the PI3K/AKT pathway." (PMID 38245694, 2024). "For total SGRQ score, 36 out of the 38 pathways identified in the airway epithelium overlapped with those in blood, including small and non-small cell lung cancer and mTOR signaling pathways." (PMID 36672643, 2023). "Respectively, the combined treatment inhibited the progression of non-small-cell lung cancer (NSLC) by blocking the PI3K/Akt/mTOR pathway, thus inducing cell apoptosis and limiting cell proliferation, migration, and metastasis." (PMID 37176897, 2023). "Key players in these pathways include EGFR, PI3K, Akt, mTOR, and PTEN, which are commonly mutated in lung cancer, and are found to be upregulated by morphine via MOR in non-small-cell lung cancer." (PMID 36835812, 2023). "In line with our findings, activating the AMPK/mTOR signaling pathway, baicalin suspresses the migration and proliferation of human non-small cell lung carcinoma cells." (PMID 37816017, 2023). "SETD5 enhances the cytodryness of non-small-cell lung cancer (NSCLC) through the PI3K/Akt/mTOR pathway." (PMID 37941780, 2023). "ROR1 silencing in non-small cell lung cancer (NSCLC) cell lines led to decreased activity of the PI3K/AKT/mTOR signaling pathway, which is related to apoptosis and antiproliferative effects on tumor cells." (PMID 36873868, 2023). "In previous studies, it has been found that diaporine is not only a modulator of macrophage differentiation but also hinders the growth of non-small-cell lung cancer (NSCLC) by regulating the miR-99a/mTOR signaling pathway." (PMID 36013267, 2022). "A previous study has reported that mTOR inhibition by rapamycin treatment inhibits cellular PD-L1 levels in non-small cell lung cancer cells." (PMID 36077620, 2022). "Gedatolisib is a dual PI3K/mTOR inhibitor, and levels of mRNAs encoding HPRT1 (a key component of the purine rescue pathway) differ significantly between non-small cell lung cancer cells that are sensitive or resistant to gedatolisib." (PMID 35663326, 2022). "Coincidentally, our previous study demonstrated that phycocyanin diminished the viability of non-small-cell lung cancer cells via the induction of autophagy by downregulating p-mTOR expression, which was in line with the present results." (PMID 37430932, 2022). "Recent research indicated that high expression of miR-224 in CAFs facilitated proliferation, EMT and metastasis of non-small cell lung cancer cells by the SIRT3/AMPK/mTOR/ HIF1α signaling pathway." (PMID 35589690, 2022). "The anticancer drug sotrexoflavone induces autophagy in non-small-cell lung cancer A549 by blocking the PI3K/AKT/mTOR signaling pathway, accelerating A549 cell death." (PMID 35465266, 2022). "Tumorigenesis results from multiple factors, and abnormal activation of the PI3K-Akt-mTOR pathway is a frequent event in the non-small cell lung cancer development." (PMID 35331190, 2022). "Rapamycin-insensitive companion of mTOR (RICTOR) amplification promotes non-small cell lung cancer proliferation via generation of mTORC2." (PMID 35859795, 2022). "miR-181 inhibits autophagy in non-small-cell lung cancer by promoting PTEN/PI3K/AKT/mTOR signalling to affect the occurrence and development of tumours." (PMID 35883139, 2022).
non-small cell lung carcinoma (continued). "The observed activation of PI3K/AKT/mTOR signaling and corresponding increase in AKT phosphorylation in non-small cell lung cancer (NSCLC) tumor specimens (50–73%) was associated with poor disease prognosis." (PMID 35918763, 2022). "In conclusion, 24MD with benzoxazine dimer analogs can induce both ACD and apoptosis in non-small cell lung cancers (NSCLCs) by targeting mTOR suppression." (PMID 36234769, 2022). "Han and colleagues found that FN1 stimulated non-small cell lung cancer cell proliferation by activating the mammalian target of rapamycin, mTOR." (PMID 33962392, 2021). "As a result, targeting the PI3K/Akt/mTOR pathway has been an area of intense research interest in non-small cell lung cancer." (PMID 34316328, 2021). "For example, Resveratrol has been shown to induce protective autophagy and exert anticancer activity in non-small cell lung cancer by inhibiting Akt/mTOR and activating the P38-MAPK pathway." (PMID 34512368, 2021). "A previous outcome elucidates that miR-410-3p participates in the EMT and radio resistance by activating PTEN/PI3K/mTOR pathway in non-small cell lung cancer." (PMID 34872453, 2021). "Tripartite motif containing 25 (TRIM25) can polyubiquitinate PTEN and activate the AKT/mTOR pathway in non-small cell lung cancer." (PMID 34805185, 2021). "This study provides preclinical information regarding ETD, which exhibits promising antimetastatic activity against non-small-cell lung cancer through Akt/mTOR/p70S6K-induced actin reorganization and MMPs expression." (PMID 33758209, 2021). "HCG18 showed potential effects on pathways in cancer, non-small cell lung cancer, endometrial cancer, and mTOR signaling pathway." (PMID 34615480, 2021). "Significant rational is available for specific targeting of PI3K/AKT/mTOR pathway in the treatment of non-small cell lung cancer (NSCLC)." (PMID 33889306, 2021). "In non-small cell lung cancer, increased ROS acts as the initial signal to inhibit the mTOR signaling pathway, thus resulting in the activation of ACD." (PMID 34692691, 2021). "6-shogaol inhibits cell survival and stimulates autophagy by suppressing the AKT/mTOR pathway in human non-small cell lung cancer A549 cells." (PMID 34575981, 2021). "For example, as a ceRNA for miR-520a-3p, lncRNA non-coding RNA activated by DNA damage (NORAD) was found to modulate the PI3K/AKT/mTOR signaling pathway to promote the occurrence and progression of non-small cell lung cancer." (PMID 34036383, 2021). "The inhibition of mTOR by RAD001 or rapamycin enhances radiosensitization via the induction of autophagy in non-small cell lung cancer in vivo." (PMID 33824475, 2021). "Recent studies indicated that the expression of Beclin1 and mTOR were well correlated with survival and clinical stages of human non-small cell lung cancer (NSCLC) patients." (PMID 33773561, 2021). "The overexpression of miR-142-3p attenuated autophagy by regulating the PI3K/AKT/mTOR pathway and enhanced the chemosensitivity of non-small cell lung cancers." (PMID 32373608, 2020). "In contrast, genes related to low C1QTNF6 expression were enriched in the mTOR signaling pathway, non-small-cell lung cancer, Notch signaling pathway, TGF-β signaling pathway, and ubiquitin-mediated proteolysis." (PMID 33123583, 2020). "DHA and gefitinib co-administration also downregulate the levels of phosphorylated p-AKT and p-mTOR to inhibit the proliferation and migration of non-small cell lung cancer cells." (PMID 33658929, 2020). "However, whether aberrant expression of phosphorylated Akt (p-Akt), phosphorylated mTOR (p-mTOR) and phosphorylated eIF4E (p-eIF4E) is associated with clinicopathological characteristics in surgically resected non-small cell lung cancer (NSCLC) has been rarely reported." (PMID 32023262, 2020).
non-small cell lung carcinoma (continued). "We demonstrate that mEAK-7 and mTOR signaling are strongly elevated in tumor and metastatic lymph nodes of patients with non-small-cell lung carcinoma compared with those of patients with normal lung or lymph tissue." (PMID 31288154, 2019). "While silencing long non-coding RNA ROR improves sensitivity of non-small-cell lung cancer to cisplatin resistance by inhibiting PI3K/Akt/mTOR signaling pathway." (PMID 31475112, 2019). "Recent studies indicate that inhibition of autophagy by andrographolide re-sensitizes cisplatin-resistant non-small cell lung carcinoma cells via activation of the Akt/mTOR pathways." (PMID 31475112, 2019). "The inhibitory effect of rosiglitazone on non-small cell lung cancer (NSCLC) cell growth was enhanced by the mTOR inhibitor rapamycin." (PMID 30424016, 2018). "Currently running trials in advanced non-small Cell Lung Cancer combining the MEK inhibitor MEK162 with the PI3Kα inhibitor BYL719 (NCT02276027) or the MEK inhibitor Selumetinib with mTOR inhibitor AZD2014 (NCT02583542) underscore their therapeutic potential." (PMID 29515122, 2018). "The mTOR inhibitor rapamycin is sensitive to non-small cell lung cancer (NSCLC) based on newly predicted drug responses versus available observations." (PMID 28768489, 2017). "It has been reported that ERBB4 and S6K2 are the direct targets of miR-193a-3p and that PIK3R3 and mTOR are the direct targets of miR-193a-5p in non-small-cell lung cancer." (PMID 28611587, 2017). "The mTOR inhibitor rapamycin was sensitive to non-small cell lung cancer (NSCLC) based on newly predicted drug responses versus available observations." (PMID 28768489, 2017). "The mTOR pathway is upregulated in non-small-cell lung cancer (NSCLC) and metformin inhibits its signaling by directly activating 5' adenosine monophosphate-activated protein kinase (AMPK) via liver kinase B1 (LKB1)." (PMID 28456789, 2017). "For example, miR-206 inhibits HGF-induced EMT process and angiogenesis via PI3K/Akt/mTOR signaling pathway in non-small-cell lung cancer.TGF-β2 induces the EMT process via activation of PI3K/Akt/mTOR signaling pathway in cultured human lens epithelial cells." (PMID 28864782, 2017). "It has been demonstrated that LARP1 expression correlates with poor prognosis of non-small cell lung cancer and promotes cellular proliferation by interacting with mTOR." (PMID 27614686, 2016). "In this regard, a recent report on non-small cell lung cancer relates poor prognosis to the up-regulation of B7-H3 by ILT-4 through PI3K/AKT/mTOR pathway." (PMID 26771843, 2016). "Previous studies have shown cardiac glycosides induces autophagic cell death in non-small cell lung cancer cells through multiple signaling pathways including mTOR deactivation, ERK1/2 activation, and JNK activation." (PMID 26910837, 2016). "Combination of MEK1/2 and PI3K/mTOR inhibitors potentiates the inhibitory effects on cell proliferation and angiogenesis in non-small cell lung carcinoma (NSCLC)." (PMID 27176481, 2016). "The tri-methyl selective KDM4A/JMJD2A demethylase is an AR coregulator expressed in PCa and is a determinant of mTOR inhibitor sensitivity in non-small cell lung cancer patients." (PMID 26461474, 2015). "Src and the mammalian target of rapamycin (mTOR) signaling are commonly activated in non-small cell lung cancer (NSCLC) and hence potential targets for chemotherapy." (PMID 26061184, 2015). "Similar data were obtained in early stage Non Small Cell Lung Cancer where angioinvasion and mTOR expression were significant predictors of poor survival at both univariate and multivariate analysis." (PMID 26097872, 2015). "Further support for this notion came from a study describing a synergistic interaction between rapamycin, an mTOR inhibitor, and erlotinib in non-small cell lung cancer cell lines." (PMID 26053020, 2015).
non-small cell lung carcinoma (continued). "Similar to the results obtained with the VPS34-inhibitor SAR405, the ULK1-inhibitor SBI-0206965 synergizes with mTOR inhibition to induce cell death in A549 non-small cell lung cancer cells." (PMID 26390974, 2015). "We have addressed the role of hamartin, phospho-tuberin (p-TSC2) and phospho-mTOR (p-mTOR) in a series of non-small cell lung cancer (NSCLC) and small cell lung cancer (SCLC) samples." (PMID 24593867, 2014). "Components of mTOR signaling pathway were silenced by shRNA in a panel of non-small cell lung cancer cell lines and protein expression of epithelial and mesenchymal markers were evaluated by immunoblotting and immunocytochemistry." (PMID 24571487, 2014). "We assessed expression of p85 and p110α PI3K subunits in non-small cell lung cancer (NSCLC) specimens and the association with mTOR expression, and studied effects of targeting the PI3K/AKT/mTOR pathway in NSCLC cell lines." (PMID 22355357, 2012). "Its over-expression was related to stimulation of non-small cell lung cancer growth through activation of Akt/mTOR/S6 kinase and inactivation of LKB1/AMP-activated protein kinase signal pathway." (PMID 22848476, 2012). "Inhibition of mTOR has been shown to decrease p21 in human non-small cell lung carcinoma cells, and, in fact, such attenuation of p21 is required for sensitization of these cells to apoptosis induced by DNA damage." (PMID 17300726, 2007). "For example, in non-small cell lung cancer (NSCLC), TRIM25 mediates the K63-linked ubiquitination of PTEN at the K266 site, and promotes the proliferation of NSCLC cells and tumor growth by activating AKT/mTOR signaling pathway." (PMID 41315221, 2025). "Likewise, the upregulation of miRNAs − 410 in non-small cell lung cancer cells has been observed in the amounts of phosphorylated Akt, mTOR, P70S6K, and 4E-BP1." (PMID 38965615, 2024). "Also, the development of mTOR pathway-related protein p-mTOR and p-S6 suppress with upregulation of miRNAs − 101-3p, which increases in the miRNAs − 101-3p depleted non-small cell lung cancer cells." (PMID 38965615, 2024). "MARK2/4 may promote the Warburg effect and cell growth of non-small cell lung cancer through AMPKα1/mTOR/HIF-1α signaling pathway." (PMID 39588377, 2024). "Moreover, aberrant activation of the PI3K/Akt/mTOR pathway facilitates the stemness maintenance of NSCLC (non small cell lung cancer) cells by upregulating chemokine (C‐X‐C motif) receptor 4 (CXCR4) and the subsequent CXCR4‐stimulated STAT3 signaling." (PMID 36226253, 2022). "Besides, FAM83D can advance epithelial-mesenchymal transition and metastasis of non-small cell lung carcinoma cells through the AKT/mTOR signal pathway, also improve the sensitivity of NSCLC cells to cisplatin." (PMID 35489022, 2022). "In addition, sertraline can regulate autophagy through the AMPK/mTOR pathway, which was found to inhibit the effect of erlotinib in the treatment of non-small cell lung cancer." (PMID 34006301, 2021). "Additionally, curcumin induces apoptosis and autophagy in human non-small cell lung cancer A549 cells by inhibiting the phosphatidylinositol 3 kinase (PI3K)/Akt/mammalian target of rapamycin (mTOR) pathway." (PMID 34497528, 2021). "A total of 178 pathways were enriched in DEGs, and the top 5 enriched pathways were the Fanconi anemia pathway, mechanistic target of rapamycin kinase (mTOR) signaling pathway, homologous recombination, non-small-cell lung cancer, and fatty acid elongation pathway." (PMID 34084771, 2021). "On the contrary, it has been shown that JNK inhibitor-mediated autophagy may increase the apoptotic effect of mTOR inhibitors in non-small-cell lung cancer cells." (PMID 32605008, 2020). "In non-small cell lung cancer, upregulation of miR-1271 contributes to the inhibition of cancer development both in vitro and in vivo by downregulation the expression of its target gene mechanistic target of rapamycin (mTOR)." (PMID 32448371, 2020).